EGFR (epidermal growth factor receptor)
Diseases named in the same sentence as EGFR in open-access papers (continued):
Sharing a sentence is not in itself a finding about the gene and the disease.
lung squamous cell carcinoma (continued). "Compared to the small cell or squamous cell lung cancer patients, more LUAD patients could benefit from the target therapies including but not limited to EGFR TKIs, VEGFR inhibitors, or c‐MET inhibitors." (PMID 39431755, 2024). "These miRNAs are predicted to modulate genes and pathways with known roles in lung tumorigenesis, including EGFR, K-RAS, and PI3K/AKT signaling, suggesting that the 3-miRNA signature is biologically relevant in adenocarcinoma and squamous cell carcinoma of the lung." (PMID 32726984, 2020). "In contrast to previous studies, in our study, treatment with the EGFR monoclonal antibody nimotuzumab did not prolong survival in squamous cell lung cancer patients." (PMID 27823977, 2017). "Our data seem to indicate that CD73 inhibition could improve the clinical effects of EGFR-TKI, especially in squamous cell lung carcinoma." (PMID 28158983, 2017). "Importantly, the data also demonstrated the potential activation of STAT3 by a number of upstream receptor tyrosine kinase signaling pathways found to be recurrently amplified in squamous cell lung carcinoma, including PDGFRA and/or KIT, EGFR, and FGFR1." (PMID 25573684, 2015). "Furthermore, others have shown that activation of FAK signaling is associated with EGFR-TKI resistance in NSCLC, although this is currently not of great importance for squamous cell carcinoma of the lung." (PMID 37445817, 2023). "Dysregulation of the mTOR pathway is more common in squamous cell lung cancer than in adenocarcinoma, and patients with mutant EGFR always show abnormal PI3K/AKT/mTOR activation, which leads to resistance to clinical treatment with EGFR-tyrosine kinase inhibitor (EGFR-TKI)." (PMID 34195072, 2021). "The analogy could also be extended to the lung squamous cell carcinoma subtype and suggests that downregulation of FOXA1 and GATA3 as well as upregulation/activation of EGFR and STAT3 as fundamental components of a generalized basal/squamous-like tumor phenotype." (PMID 26008846, 2015). "However, given that the expression of ELF3 is upregulated in several K-Ras mutant LUADs and lung squamous cell carcinomas (LSCCs), whether auranofin has therapeutic potential to repress ELF3 through inhibition of PKCί activity in EGFR mutant LUAD remains unclear." (PMID 34830169, 2021).
renal cell carcinoma (176 papers, 1998 to 2026). "For example, cytoplasmic EGFR (EGFR-C) is associated with advanced clinicopathological features and poor prognosis in renal cell carcinoma and squamous cell carcinoma of the lung." (PMID 34830108, 2021). "In contrast to many other tumors, EGFR localization to the membrane was found to be significantly associated with better patient survival in renal cell carcinoma." (PMID 28740577, 2017). "Anti‐VEGF drugs such as lenvatinib or bevacizumab combined with immunotherapy or EGFR inhibitors have shown encouraging results in FH‐deficient renal cell carcinoma, suggesting that they may also derive some benefit for patients with FH‐deficient Leydig cell tumours." (PMID 41384702, 2026). "Among these, EGFR and CD4 exhibited a protective role in renal cell carcinoma, whereas TRIB3 and ZAP70 were identified as risk factors (P - value <0.05)." (PMID 40104395, 2025). "In KIRC, EGFR overexpression is recognized as a crucial factor contributing to the initiation and progression of renal cell carcinoma." (PMID 41300698, 2025). "We found that renal cell carcinomas and differentiated thyroid cancers that responded to this drug displayed higher EGFR-scores." (PMID 40846697, 2025). "In particular, high-grade renal cell carcinoma tissues express high levels of EGFR which paralleled an increased activation of downstream mitogenic kinases." (PMID 38379085, 2024). "In another study, it was revealed that silibinin prevents the advancement of renal cell carcinoma induced by EGFR signaling through the inhibition of the EGFR/MMP-9 pathway." (PMID 38504785, 2024). "Another study revealed SMYD3 as a mediator between the von Hippel‒Lindau/hypoxia-inducible factor α (VHL-HIFα) axis and epidermal growth factor receptor (EGFR) in renal cell carcinoma." (PMID 39482529, 2024). "Li and colleagues uncovered a novel lncRNA-encoded polypeptide, termed micropeptide MIAC, which weakens cancer cell growth and metastasis and accelerates apoptosis in renal cell carcinoma by inactivating the pathway of EREG/EGFR." (PMID 38351332, 2024). "Cabozantinib is also reported to synergize with EGFR specific CAR-NK-92 cells in human renal cell carcinoma xenograft models." (PMID 35122833, 2022). "The study has shown that CAR-NK-92 cells lysed the renal cell carcinoma cells in an EGFR-specific manner." (PMID 35122833, 2022). "Since the first TKIs were introduced, researchers have focused on some hot terms such as NSCLC, EGFR, CML, EGFR-TKI, EGFR mutation, erlotinib, imatinib, osimertinib, gefitinib, targeted therapy, renal cell carcinoma, resistance." (PMID 35072634, 2022). "CAV2 is an oncogene that can promote the growth of renal cell carcinoma through the EGFR/PI3K/Akt pathway." (PMID 33968130, 2021). "We showed that a renal cell carcinoma cell line (RC21) has higher expression of EGFR as compared to other frequently used cell lines such as HEK293, A549, Hela and DLD1." (PMID 32413049, 2020). "Renal cell carcinoma proliferation depends on the EGFR-mediated pathway which is upregulated by LINC00037/EGFR complex." (PMID 33050646, 2020). "In this study, we investigated EGFR knockout as a therapeutic approach in renal cell carcinoma (RCC)." (PMID 32413049, 2020). "In our previous study, we found that the depletion of HCRP-1 obviously improved the migration and invasion abilities of renal cell carcinoma cells via EGFR–ERK signaling." (PMID 30518879, 2018). "EGFR also functions in renal cell carcinoma and is involved in the progression of renal cell carcinoma." (PMID 28122358, 2017). "Another retrospective study of 76 patients with metastatic renal cell carcinoma revealed that concomitant use of bisphosphonates and EGFR-TKIs in renal cell carcinoma patients with bone metastases probably improved treatment efficacy." (PMID 26624882, 2016). "Sorafenib is an epidermal growth factor receptor (EGFR) tyrosine kinase inhibitor that has been used in molecularly targeted therapy for advanced-stage renal cell cancer (RCC)." (PMID 25663922, 2015).
renal cell carcinoma (continued). "EGFR protein overexpression is frequent in renal cell carcinoma and correlates with the chromosome 7 polysomy and poor prognostic parameters in clear cell renal cell carcinoma." (PMID 23878753, 2013). "Reports indicate that activation of EGFR can regulate activity of sulfatases in renal cell carcinoma metastasis to promote sulfation of glycosphingolipids and enhance tumor cell invasion and metastasis." (PMID 23472069, 2013). "The top five pathways, which are more represented by the down-regulated miRNAs targets, include axon guidance, adherens junction, actin cytoskeleton regulation, ErbB (EGFR) signaling and renal cell carcinoma." (PMID 22911744, 2012). "In this study, we demonstrated the different locations of epidermal growth factor receptor (EGFR) immunostaining in renal tumorigenesis from renal cell carcinoma (RCC) and adjacent normal kidney tissues of 63 patients." (PMID 19747398, 2009). "Epidermal growth factor receptor (EGFR) and tumour growth factor alpha (TGFα) are frequently overexpressed in renal cell carcinoma (RCC) yet responses to single-agent EGFR inhibitors are uncommon." (PMID 15956968, 2005). "Claspin expression is frequently observed in EGFR-positive renal cell carcinoma cells, which may be due to the proliferation signaling induced through EGFR." (PMID 41009395, 2025). "For instance, epidermal growth factor receptor (EGFR) or mitogen-activated protein kinase (MEK1/2) kinase activity hinders the growth of renal cell carcinoma cells and enhances the growth inhibitory effects of the mammalian target of rapamycin (mTOR) inhibitor rapamycin." (PMID 41340127, 2025). "Thus, EGFR activation mediated by the VHL/HIF-2α/SMYD3 signaling cascade promotes renal cell carcinoma progression." (PMID 39482529, 2024). "This study concluded that EGFR inhibition in combination with sutininib might have a better outcome for EGFR-expressing renal cell carcinoma patients." (PMID 36497228, 2022). "More importantly, the TCPA analysis provides an independent confirmation of the high expression of EGFR in renal cell cancer and further indicates that EGFR could be a subtype specific biomarker for kidney cancer." (PMID 36221114, 2022). "Additionally, in renal cell carcinoma, concomitant overexpression of the EGFR and erbB-2 was correlated with dedifferentiation and metastasis." (PMID 33803354, 2021). "The epidermal growth factor receptor (EGFR) signaling pathway plays a critical role in the pathogenesis and progression of renal cell carcinoma, suggested that LRRK2 may play an important role in ccRCC as well." (PMID 34217264, 2021). "RC21 is a renal cell carcinoma cell line with overexpressed EGFR." (PMID 32413049, 2020). "Furthermore, EGFR loss induced G2/M phase arrest and resulted in an increased resistance to TNF-related apoptosis-inducing ligand (TRAIL) in renal cell carcinoma." (PMID 32413049, 2020). "Similarly, increased EGFR expression occurs in a fraction of patients who have renal cell carcinoma (RCC) with an unfavorable histologic phenotype." (PMID 31330946, 2019). "A subset of renal cell carcinoma (RCC) patients has been shown to respond to anti-EGFR therapy." (PMID 28326248, 2014). "High expression of EGFR is considered to be an unfavourable prognostic factor in patients with a variety of tumours, including renal cell carcinoma (RCC)." (PMID 14520458, 2003). "Thus, ablation of overexpressed EGFR by CRISPR/Cas9 alone or in combination with sunitinib may be a new treatment option for renal cell carcinoma." (PMID 32413049, 2020). "GA inhibited the proliferation of renal cell carcinoma (RCC) cell lines 786-O and A498 by inactivating the epidermal growth factor receptor (EGFR) signaling pathway with the downregulation of p-Akt and p-Erk expression." (PMID 33260759, 2020).
renal cell carcinoma (continued). "Two retrospective studies indicated that bisphosphonates combined with sunitinib/sorafenib could improve the response rate, PFS and OS in renal cell carcinoma with bone metastases, which suggested that the combination of bisphosphonates and EGFR-TKIs probably also bring benefits to NSCLC." (PMID 26624882, 2016). "Overexpression of EGFR in renal cell carcinoma (RCC) has been shown in various research, ranging from 40-80%." (PMID 22475688, 2012). "The association between EGFR expression and prognosis in renal cell carcinoma (RCC) is not clear." (PMID 14520458, 2003). "Zhang constructed an EGFR-specific third-generation CAR, confirming the specific killing ability of CAR-modified NK-92 cells against renal cell carcinoma (RCC) cell lines." (PMID 40260240, 2025). "In renal cell carcinoma (RCC), overexpressed micropeptide MIAC significantly reduces the capacity of cells to proliferate and migrate by binding to AQP2 and reducing EREG/EGFR expression in vitro and in vivo." (PMID 39443468, 2024). "For instance, HIF-induced upregulation of the caveolin increased EGFR dimerization and phosphorylation, leading to EGF-independent activation of EGFR signaling in renal cell carcinoma cell lines." (PMID 35681691, 2022). "Combining EGFR CAR NK cells with oncolytic herpes simplex virus-1 or chemotherapeutics showed synergistic effects on breast cancer and renal cell carcinoma (RCC) in mice, respectively." (PMID 34943898, 2021). "In this study, we used MET-, EGFR-, and HER2-targeted immuno-PET to detect RTK protein levels after targeted therapy in a renal cell carcinoma (RCC) patient–derived xenograft (PDX) model." (PMID 32646879, 2021). "Moreover, in renal cell carcinoma, recent evidence indicates that the membranous expression of EGFR has a correlation with poorly differentiated and high nuclear grade tumours, while nuclear EGFR expression is high in well differentiated and low nuclear grade tumours." (PMID 29615051, 2018). "Treatment with gefitinib, a selective EGFR RTK, resulted in decreased cell proliferation and decreased microvascular density and VEGF levels in murine renal cell carcinoma." (PMID 27245053, 2016). "Previous studies have revealed altered expression of epidermal growth factor (EGF) receptor (EGFR)-family members and their endogenous inhibitor leucine-rich and immunoglobulin-like domains 1 (LRIG1) in renal cell carcinoma (RCC)." (PMID 22554477, 2012). "Previous studies have revealed altered expression of epidermal growth factor receptor (EGFR)-family members and their endogenous inhibitor leucine-rich and immunoglobulin-like domains 1 (LRIG1) in renal cell carcinoma (RCC)." (PMID 22554477, 2012). "In all, 31 renal cell carcinomas (RCCs) were examined for expression of the potential tumour suppressor LRIG1 (formerly Lig-1) and the epidermal growth factor receptor (EGFR)." (PMID 14520461, 2003). "Moreover, cabozantinib can increase EGFR in RCC cells and reduce PD-L1 membrane surface expression, enhancing the killing ability of CAR-NK-92 cells against renal cell carcinoma." (PMID 40052147, 2025). "Similarly, a third-generation CAR targeting epidermal growth factor receptor (EGFR) in NK-92 cells, combined with the kinase inhibitor cabozantinib, effectively lysed EGFR-positive renal cell carcinoma (RCC) cells and improved tumour homing." (PMID 39450176, 2024). "In a recent study, PKM2 was reported to regulate the transactivation of β-catenin in response to epidermal growth factor receptor (EGFR) activation and was also suggested to play a critical role in mediating β-catenin nuclear localization in renal cell carcinoma treated with metformin." (PMID 35637461, 2022). "It was recently demonstrated that EGFR is directly O-GlcNAcylated and that OGT knock-down downregulates EGFR and its downstream PI3K/AKT pathway, and promotes cell cycle arrest and apoptosis in 786-O renal cell carcinoma cells." (PMID 36059648, 2022).
renal cell carcinoma (continued). "The genes involved in EGFR tyrosine kinase inhibitor resistance, the Ras signaling pathway, mTOR signaling pathway, PI3K-Akt signaling pathway and renal cell carcinoma are related to angiogenesis, which has also been confirmed as an important way to cope with hypoxia pressure." (PMID 36552492, 2022). "Similarly, for renal cancer, EGFR and TIM-1 are established tumor biomarkers for which immunotherapy has been proposed and a phase I clinical trial with the goal to treat renal cell carcinoma with a TIM-1 targeting antibody indicated efficacy with manageable adverse effects." (PMID 36221114, 2022). "Targeting several cell surface RTKs simultaneously, in addition to EGFR, or inactivating intracellular kinases that function as converging hubs of deregulated signalling pathways may be an effective therapeutic strategy for treating FLCN-dependent renal cell cancers." (PMID 28656962, 2017). "This is not an in vitro-only phenomenon; renal cell carcinomas growing in FLCN KO mouse kidneys display strong activation of the EGFR signalling pathway and treatment of FTC-133 FLCN−/− mouse xenografts with the EGFR inhibitor Afatinib slowed tumour growth." (PMID 28656962, 2017).
astrocytoma (169 papers, 1992 to 2026). "EGFRvIII, characterized by an intragenic deletion spanning exons 2 to 7 affecting the extracellular domain, is closely associated with EGFR gene amplification, primarily found in high-grade astrocytomas like GBMs, with occasional exceptions." (PMID 39063215, 2024). "Secreted PLA2, PLA2G2A-encoded protein, was discovered to induce proliferation in astrocytoma through the epidermal growth factor receptor (EGFR), contributing to worsening the prognosis of a tumor in an inflammatory microenvironment." (PMID 36091778, 2022). "TERTp mutation, EGFR amplification, and diagnosis of “astrocytoma, grade 4” were significant factors in the group of all IDH-wild-type astrocytomas." (PMID 34257410, 2021). "These factors and TERTp mutation, EGFR amplification and the diagnosis of “astrocytoma, grade 4” were analysed by Cox proportional hazard modelling." (PMID 34257410, 2021). "In the present study, correlation analysis showed that TERTp mutation was associated with EGFR gain and PTEN loss, and + EGFR/− PTEN astrocytoma always accompanied TERTp mutation." (PMID 34257410, 2021). "According to cIMPACT-NOW update 3, IDH-wild-type astrocytomas with any of the following factors show poor prognosis: combination of chromosome 7 gain and 10 loss (+ 7/− 10), and/or EGFR amplification, and/or TERT promoter (TERTp) mutation." (PMID 34257410, 2021). "WHO grade, TERTp mutation, EGFR amplification and diagnosis of “astrocytoma, grade 4” were good predictors of IDH-wild-type astrocytomas in Kaplan–Meier analysis, but Cox proportional hazard modelling detected no significance for OS in these factors." (PMID 34257410, 2021). "PTEN loss was detected in 11 astrocytomas and 3 were homozygous losses and 8 were hemizygous losses, 6 of which were coincided with EGFR gains." (PMID 34257410, 2021). "ANXA1 is also known to be involved in proliferation, differentiation and apoptosis, serves as a substrate for EGFR, and is implicated in tumor progression of astrocytoma." (PMID 31952211, 2020). "Molecular anomalies typical for astrocytomas (TP 53 mutations, EGFR gene overdosage, CDKN2A deletion; LOH 10p, LOH 10q) identified in original tumours used for the generation of cell cultures were applied as potential markers of tumour cells." (PMID 25788865, 2014). "EGFR activation is a key step in the tumor growth of a variety of carcinomas, and is associated with the malignancy of astrocytoma." (PMID 25364437, 2014). "Many of the genes have in fact been implicated in development of astrocytoma, including EGFR, HIF-1α, c-Myc, WNT5A, and IDH3A." (PMID 23737970, 2013). "On the contrary, loss of PTEN locus were more frequent in high-grade astrocytomas (49/65, 75.4%) than in low-grade astrocytomas (4/12, 33.3%) (p = 0.007), and EGFR amplification was only detected in high-grade tumors (26/73, 35.6%) (p = 0.002)." (PMID 24079673, 2013). "Others have reported that faster progressing mutant IDH1-driven astrocytomas had increased copy numbers in EGFR, MYC, MET, and CDK6 compared to slower-progressing patients." (PMID 40188944, 2025). "In contrast to GB, IDH-mutant astrocytomas often harbor wild-type EGFR and PTEN genes, along with MGMT promoter methylation." (PMID 41426972, 2025). "IDH1/2-mutant astrocytomas rarely exhibited EGFR amplifications (3%), which were confined to high-grade tumors." (PMID 41377022, 2025). "In IDH1/2-mutant astrocytomas, EGFR amplifications were rare (1.7%) but confined to higher-grade tumors (grade 3: 5 tumors, grade 4: 12 tumors)." (PMID 39164213, 2025). "In accordance with our findings in macrophages, P2Y11/IL-1R- or P2Y11/CXCR7-driven CCL20 production in astrocytoma cells depended on EGFR as well as on ERK and appeared to occur in an EGFR/CXCR7-ligand-independent manner." (PMID 38472446, 2024).